MRC2 (mannose receptor C-type 2)
Description:
May play a role as endocytotic lectin receptor displaying calcium-dependent lectin activity. Internalizes glycosylated ligands from the extracellular space for release in an endosomal compartment via clathrin-mediated endocytosis. May be involved in plasminogen activation system controlling the extracellular level of PLAUR/PLAU, and thus may regulate protease activity at the cell surface. May contribute to cellular uptake, remodeling and degradation of extracellular collagen matrices. May play a role during cancer progression as well as in other chronic tissue destructive diseases acting on collagen turnover. May participate in remodeling of extracellular matrix cooperating with the matrix metalloproteinases (MMPs).
Synonyms: CD280; CLEC13E; ENDO180; KIAA0709; UPARAP
Tractability: Antibody: UniProt predicts a signal peptide or a membrane-spanning region. PROTAC: UniProt records ubiquitination sites on it; ubiquitination databases record sites on it.
Gene: Protein-coding gene on chromosome 17 (62,627,670 to 62,693,597, forward strand). Ensembl gene ENSG00000011028.
Subcellular location: Membrane
Pathways (Reactome):
Immune System: Cross-presentation of soluble exogenous antigens (endosomes)
Gene Ontology:
Molecular function: collagen binding; protein binding; transmembrane signaling receptor activity
Biological process: collagen catabolic process; osteoblast differentiation; receptor-mediated endocytosis
Cellular component: focal adhesion; membrane; plasma membrane
Genetic constraint (gnomAD): Loss-of-function variants: 84 observed, 195.93 expected, observed/expected ratio (o/e) 0.43, 90% interval 0.36 to 0.51. The upper end of that interval is the gene's LOEUF score, 0.51, which puts it in group 2 of 6, group 1 being the genes least tolerant of losing a copy. Missense variants: 1,676 observed, 1,952.4 expected, observed/expected ratio (o/e) 0.86, 90% interval 0.82 to 0.89. Synonymous variants: 798 observed, 779.47 expected, observed/expected ratio (o/e) 1.02, 90% interval 0.96 to 1.09.
Homologues: Orthologues: chimpanzee MRC2 (99% identical), macaque MRC2 (99% identical), dog MRC2 (95% identical), guinea pig MRC2 (92% identical), pig MRC2 (91% identical), mouse Mrc2 (91% identical), rat Mrc2 (90% identical), rabbit MRC2 (63% identical), tropical clawed frog mrc2 (61% identical), zebrafish mrc2 (50% identical). Paralogues in human: PLA2R1 (33% identical), MRC1 (32% identical), LY75 (31% identical), CD302 (3% identical).
Diseases named in the same sentence as MRC2 in open-access papers:
MRC2 is named in the same sentence as 97 diseases in open-access papers, as found by Europe PMC text mining. Sharing a sentence is not in itself a finding about the gene and the disease. The quoted sentences say what the papers report.
breast cancer (14 papers, 2012 to 2024). A primary or metastatic malignant neoplasm involving the breast. "We further checked the expression level of Mrc2 in the 4 subtypes of BRCA1-deficient mouse mammary tumors, and found Mrc2 was highly expressed in the mesenchymal-like tumors when compared to other 3 subtypes." (PMID 34815798, 2021). "For CNV biomarkers, MRC2 amplification and copy number gain in basal-like breast cancer may be linked to tumorigenesis and progression." (PMID 39720180, 2024). "Furthermore, from candidate markers for BRCA1 mutant tumors, we discovered and validated one oncogene Mrc2, whose loss could reduce mammary tumor growth in vitro and in vivo." (PMID 34815798, 2021). "As knockout of Mrc2 inhibits cell growth in both B477 and G600 cells, we wanted to further study the function of MRC2 in mammary tumors." (PMID 34815798, 2021). "It was consistent with the results from the Palmieri group, reporting that MRC2 was an accuracy prognostic marker for breast cancer metastases." (PMID 25162823, 2014). "Recently, there have been accumulating reports showing that MRC2 is aberrantly up-regulated in a variety of cancers and closely involved in cancer metastasis including breast cancer, prostate cancer, head stroma, and neck cancer." (PMID 25162823, 2014). "Spheroid cultures of CAFs transfected with Endo180 (Mrc2) siRNAs showed reduced viability and altered contractility; and systemic deletion of Mrc2 significantly reduced tumor burden and metastatic progression of 4T1 mouse mammary carcinoma cells in vivo." (PMID 36671452, 2022). "Besides, knockdown of MRC2 in human breast cancer cell lines: MCF7, MDA-MB-231, and MDA-MB-436 could also decelerate the cell proliferation, and reduce the mRNA levels of proliferation markers CCND1 and MKI67." (PMID 34815798, 2021). "Breast cancers that express high levels of Endo180 receptor (Mrc2) mRNA, which is expressed in myCAFs, are less sensitive to anti-PD-L1 and anti-CTLA4 ICIs in murine models and in human BC tissues." (PMID 39735530, 2024).
osteosarcoma (12 papers, 2016 to 2026). A usually aggressive malignant bone-forming mesenchymal neoplasm, predominantly affecting adolescents and young adults. "For the first time they have demonstrated that a mouse monoclonal antibody targeting the collagen receptor Endo180 (CD280, MRC2 uPARAP) can prevent osteolysis and bone destruction in a syngeneic model of advanced osteosarcoma." (PMID 26576691, 2016). "Within pediatric data sets, a comparison of cancer samples and normal tissue from the NCI OncoGenomics database also demonstrates higher MRC2 expression in the majority of sarcoma samples compared with the mean normal tissue expression, with notable elevation of MRC2 expression in osteosarcomas." (PMID 36399638, 2023).
prostate carcinoma (6 papers, 2014 to 2022). A carcinoma that arises from epithelial cells of the prostate gland. "The type I transmembrane collagen receptor Endo180 (CD280, CLEC13E, KIAA0709, MRC2, TEM9, uPARAP) is as a strong prognostic indicator for prostate cancer survival." (PMID 26567111, 2016). "Therefore, it was demonstrated that TGFβ1 regulated MRC2 expression in HCC, which is consistent with the findings in prostate cancer and glioblastoma multiforme." (PMID 25162823, 2014).
breast tumor (5 papers, 2012 to 2021). "Previous study reported that MRC2 is mainly expressed in the stromal cells but not the epithelial cells of mammary glands 60 and only expressed in some breast tumor cells." (PMID 34815798, 2021). "Located within the inactive TADs, five of the six aforementioned non-ATC loci (except EFCAB3) were highly methylated at shore regions of CpG island promoters (i.e., TBX2, TBX4, MRC2, and MARCH10) and non-CpG island promoter (i.e., NACA2) in 77 breast tumors compared to 10 normal controls (ref. #)." (PMID 32408897, 2020).
diabetic nephropathy (5 papers, 2021 to 2025). "Mannose receptor C (MRC2) pertained to the mannose receptor protein family and was validated to be upregulated in the kidneys of diabetic nephropathy mice." (PMID 40357787, 2025). "In a recent study, MRC2 has been found to be playing an important role in diabetic nephropathy as its level increases in kidneys but its knockdown promotes cellular apoptosis showing its role as potential biomarker for diabetic nephropathy." (PMID 39219798, 2024). "Upregulated MRC2 expression has been detected in cancer tissues as well as in the peripheral blood of patients with diabetic nephropathy." (PMID 37040172, 2023). "By complementary DNA chip screening and analysis, we found that the expression of MRC2 was upregulated in the kidneys of mice with diabetic nephropathy." (PMID 34012764, 2021). "This work studied the effect of MRC2 on diabetic nephropathy." (PMID 34012764, 2021). "However, the role of MRC2 in diabetic nephropathy is still unclear." (PMID 34012764, 2021).
glioblastoma (5 papers, 2014 to 2024). The most malignant astrocytic tumor (WHO grade IV). "MRC2 (Mannose Receptor C Type 2) is a mannose receptor whose expression is upregulated and associated with prognosis in some types of cancer such as glioblastoma, bladder, ovarian, and renal cancer." (PMID 38252632, 2024). "In glioblastoma multiforme, it was found that MRC2 was over-expressed in tumor tissues and attributed to mediating tumor cells invasion via collagen-containing matrices." (PMID 25162823, 2014). "Astrocyte subpopulation B (combined from all three brain regions) is mostly correlated with the mesenchymal glioblastoma gene signature, as the enriched genes in this gene set (e.g., Scpcp1, Rac2, Blcrb, Mrc2, Cd14, and C5ar, among others) are upregulated in this subpopulation." (PMID 30957015, 2019).
renal fibrosis (5 papers, 2015 to 2023). A final common manifestation of a wide variety of chronic kidney diseases characterized by glomerulosclerosis and tubulointerstitial fibrosis. "Mrc2-deficient mice showed exacerbated renal fibrosis and renal parenchymal damage following unilateral ureteral obstruction." (PMID 37498303, 2023). "Renal fibrosis was significantly worse in Mrc2-deficient mice, which was related to lower collagen turnover." (PMID 26618160, 2015). "Also, in a mouse model of renal fibrosis, disruption of MRC2 (genetic knock-out or chemical inhibitor) has been shown to enhance the fibrotic phenotype." (PMID 36531712, 2022). "In addition, treatment of wild-type mice with a cathepsin inhibitor, which blocks the proteases implicated in Mrc2-mediated collagen degradation, worsened UUO-induced renal fibrosis." (PMID 26618160, 2015).
sarcoma (5 papers, 2017 to 2026). A usually aggressive malignant neoplasm of the soft tissue or bone. "A similar picture emerges assessing MRC2 expression in sarcoma gene-expression profiling data sets, highlighting the potential of Endo180 as a therapeutic target." (PMID 36399638, 2023). "Here, we report the first in vivo assessment of an Endo180 (MRC2)-directed ADC targeting in sarcoma." (PMID 36399638, 2023). "Here, we show high levels of Endo180 protein in the majority of STS of different subtypes, and upregulated MRC2 expression in multiple sarcoma data sets." (PMID 36399638, 2023). "Lower Endo180 protein levels in the SK-UT-1 and G-402 cell lines reflects lower MRC2 expression in the CCLE data set compared with the other sarcoma cell lines." (PMID 36399638, 2023).
endometriosis (4 papers, 2016 to 2025). The growth of functional endometrial tissue in anatomic sites outside the uterine body. "In a murine model of endometriosis, the high abundance of MRC2 in endometrial stromal cells was found to be essential for the differentiation of regulatory T cells (Tregs) in coincubation experiments." (PMID 40001591, 2025). "Compared with that in the vector group, the percentage of Treg cells increased in the MRC2-silenced group, especially CD4high Treg cells, which demonstrate that MRC2 plays a key role in the differentiation of Treg cells in endometriosis." (PMID 27906184, 2016). "Consistently, the percentage of Treg increased when MRC2-shRNA was administered in the peritoneal cavity of endometriosis-disease mice model." (PMID 27906184, 2016). "Another promising treatment option is based on the demonstration that the estrogen – indoleamine 2,3-dioxygenase-1 (IDO1) – mannose receptor C, type 2 (MRC2) axis participates in the differentiation and function of Tregs and is involved in development of endometriosis." (PMID 35935991, 2022). "Moreover, the possibility that MRC2 influences the biological activities of ESCs in endometriosis remains to be explored." (PMID 27906184, 2016). "According to the findings above, MRC2 is downstream to IDO1, and IDO1 is involved in the differentiation of Treg in ectopic lesion, hinting the possibility that MRC2 may participate in the activity that IDO1 regulates the differentiation of Treg in endometriosis." (PMID 27906184, 2016). "The mannose receptor C, type 2 (MRC2), was found to be lower in ectopic endometrial stromal cells compared to normal ones, whereas peritoneal dendritic cells in endometriosis showed heightened mannose receptor expression." (PMID 40508002, 2025).
glioma (4 papers, 2010 to 2024). A benign or malignant brain and spinal cord tumor that arises from glial cells (astrocytes, oligodendrocytes, ependymal cells). "Previous studies confirmed that downregulation of MRC2 expression reduced the tumor migration and collagen invasion, suggesting active involvement of MRC2 in glioma cell invasion." (PMID 36188226, 2022). "In silico analyses of independent gene expression datasets in ONCOMINETM revealed that Endo180 (MRC2) transcripts were significantly upregulated in grade IV gliomas, i.e. GBMs, versus grade III gliomas." (PMID 20339555, 2010). "We excluded genetic and epigenetic regulation as no genomic amplification of the Endo180 locus (MRC2) at 17q23 was detected in 11 glioma cell lines and the Endo180 promoter was unmethylated in all cell lines tested, with the exception of UW479." (PMID 20339555, 2010).
lung fibrosis (4 papers, 2021 to 2024). "The inadequate upregulation of MRC2 we have described in pulmonary fibrosis could have multiple downstream consequences which we intend to explore further in future work." (PMID 38378719, 2024). "By contrast in a spontaneously resolving model of fibrosis (the bleomycin lung fibrosis model in C57Bl\6 mice) there is a positive correlation between collagen and Mrc2 expression in mouse lung and the relationship is not diminished under conditions of fibrosis." (PMID 38378719, 2024).
rhabdomyosarcoma (3 papers, 2017 to 2025). A rare aggressive malignant mesenchymal neoplasm arising from skeletal muscle. "Finally, gene expression in rhabdomyosarcomas from the ITCC data sets shows increased MRC2 expression compared with normal skeletal muscle." (PMID 36399638, 2023).
bone sarcoma (2 papers, 2023 to 2026). A sarcoma that arises from the bone. "Analysis of expression data from the CCLE is consistent with the IHC staining and gene-expression analysis of primary tumors, showing significantly higher MRC2 expression in both STS and bone sarcoma cell lines compared with breast or colorectal cancer cell lines." (PMID 36399638, 2023).
hepatocellular carcinoma (2 papers, 2009 to 2014). A malignant tumor that arises from hepatocytes. "This study attempted to determine MRC2 expression on hepatocellular carcinoma (HCC) and its significance on postsurgical prognosis of HCCs." (PMID 25162823, 2014).
leukemia (2 papers, 2017 to 2022). A malignant (clonal) hematologic disorder, involving hematopoietic stem cells and characterized by the presence of primitive or atypical myeloid or lymphoid cells in the bone marrow and the blood. "Fibrinogen and collagen in plasma will bind to the surface of GDYO nanosheets, increasing the interaction of GDYO on ITGB2 and MRC2, respectively, and thereby enhancing the anti-leukemia effect of GDYO against DNMT3A-mutant AML cells." (PMID 36163326, 2022). "GDYO enhanced interaction on ITGB2 and MRC2 with mouse plasma protein absorption, and improved the anti-leukemia effect in vitro, which partially revealed the mechanism of effective therapeutic effect in mice AML model." (PMID 36163326, 2022). "In summary, the binding of GDYO to both ITGB2 and MRC2 is indispensable for its anti-leukemia effect." (PMID 36163326, 2022).
melanoma (2 papers, 2021 to 2025). A malignant, usually aggressive tumor composed of atypical, neoplastic melanocytes. "Endo180 (MRC2), a receptor enriched on myCAFs, has been shown to suppress CD8+ T cell infiltration and limit the efficacy of αPD-1/αCTLA-4 in murine models and melanoma patients." (PMID 40940809, 2025).
metastatic melanoma (2 papers, 2022 to 2024). A melanoma that has spread from its primary site to another anatomic site. "Notably, the immunotherapeutic response group was associated with lower MRC2 expression in metastatic melanoma and advanced urothelial carcinoma cohort." (PMID 36188226, 2022). "The results elucidated the potential immunotherapeutic response prediction function of MRC2 in metastatic melanoma and advanced urothelial carcinoma." (PMID 36188226, 2022). "Intriguingly, when analyzing the immunotherapeutic response in a cohort of GSE78220 and IMvigor210, the response group proved the lower MRC2 expression level in metastatic melanoma with pembrolizumab (p = 0.071) and advanced urothelial cancer with atezolizumab (p = 0.0046)." (PMID 36188226, 2022).
prostate tumor (2 papers, 2016 to 2021). "In fact, the elevation of MRC2 protein level has been frequently observed in multiple cancer types, including breast and prostate tumors." (PMID 34336102, 2021).
age (1 paper, 2020). A temporal measurement of the time period elapsed since an identifiable point in the life cycle of an organism. "Of these, Mmp2 and Mrc2 are reduced in atria after 2 weeks of exercise which is of particular interest because these genes are also reduced in the age-related fibrosis of multiple tissues and AF is strongly linked to aging." (PMID 33424629, 2020).
allergic asthma (1 paper, 2020). A asthma with a basis in a pathological type I hypersensitivity reaction. "Moreover, the MRC2 receptor blocker mannan, derived from Saccharomyces cerevisiae, effectively inhibits inflammation and airway smooth muscle remodeling in a humanized MRC2-overexpressing mouse model of allergic asthma." (PMID 33036262, 2020).
aneurysm (1 paper, 2020). Bulging or ballooning in an area of an artery secondary to arterial wall weakening. "To determine whether reduced MRC2 is a feature of clinical MFS aneurysm, we assessed MRC2 expression via western blot from tissue lysates obtained from MFS patients undergoing aneurysm repair surgery." (PMID 33230159, 2020).
aortic aneurysm (1 paper, 2020). A ruptured aneurysm located in the wall of the proximal portion of the descending aorta proceeding from the arch of the aorta. "Collectively these data identify MRC2 down-regulation as a novel marker of MFS aortic aneurysm identified in vitro by shotgun proteomic techniques." (PMID 33230159, 2020).
Aortic root aneurysm (1 paper, 2020). An abnormal localized widening (dilatation) of the aortic root. "Single protein-level data from both iPSC SMCs and primary MFS aortic root aneurysm tissue confirmed elevated integrin αV and reduced MRC2 in clinical disease specimens, validating the iPSC iTRAQ findings." (PMID 33230159, 2020). "Reduced MRC2 was confirmed in human MFS aortic tissue lysates from patients with aortic root aneurysms (n = 3) compared to a healthy organ donor control (MRC2 aortic root/ascending: MFS 0.6 vs. control 1.1-fold)." (PMID 33230159, 2020).
arrhythmogenic right ventricular cardiomyopathy (1 paper, 2022). "The KEGG pathway analysis showed that the top three significantly enriched signaling pathways by the mRNAs in mRC2 were the MAPK signaling pathway, arrhythmogenic right ventricular cardiomyopathy, and hypertrophic cardiomyopathy." (PMID 36077928, 2022).
asthma (1 paper, 2017). "Investigation to determine possible association between MRC2 SNPs and asthma is underway." (PMID 28835901, 2017).
autoimmune uveitis (1 paper, 2025). An autoimmune form of uveitis (disease). "These proteins, especially MRC2 and THBS1, emerge as potential markers for assessing RMG activation, retinal immune balance, and the maintenance of ocular immune privilege in autoimmune uveitis." (PMID 40001591, 2025). "The reduced abundance of MRC2 in uveitic RMG reflects a shift in their immunological and functional profile during autoimmune uveitis." (PMID 40001591, 2025).
cardiac hypertrophy (1 paper, 2023). "Six hub genes (TANC2, ADAMTS2, DYNLL1, MRC2, EGR1, and OTUD1) showed anomaly trend in cardiac hypertrophy." (PMID 37498303, 2023). "A total of six hub genes (TANC2, ADAMTS2, DYNLL1, MRC2, EGR1, and OTUD1) were considered cardiac hypertrophy and HF regulators." (PMID 37498303, 2023).
lung adenocarcinoma (1 paper, 2015). A carcinoma that arises from the lung and is characterized by the presence of malignant glandular epithelial cells. "Mutations in RHPN2 (5%), GLI3 (4%) and MRC2 (2%) have not been reported previously as driver genes in lung adenocarcinomas but were recurrently observed in our cohort and are nominated to be significantly mutated." (PMID 26647728, 2015).